IL10 (interleukin 10)
Diseases named in the same sentence as IL10 in open-access papers (continued):
Sharing a sentence is not in itself a finding about the gene and the disease.
lupus (continued). "Among the splenic B10 cells, both marginal-zone B (MZ B) cells and T2-MZP B cells have been shown to have a protective effect in mouse models of lupus and autoimmune arthritis due to their IL-10 competency." (PMID 28261223, 2017). "Specifically, anti-CD40 Ab administration induced the differentiation of T2 and MZ B cells and expanded the population of IL-10+ Bregs in vitro and in vivo, resulting in significantly improved renal disease and controlled progression of lupus in mice." (PMID 28261223, 2017). "Together, these results suggest that gut microbiota can promote an anti-inflammatory environment in the gut of lupus-prone mice, leading to induction of IL-10 that enters the circulation to provide systemic immunosuppression." (PMID 28697806, 2017). "Healthy donors responded to the peptides by proliferating and producing higher levels of both IFN-γ and IL-17, whereas PBMC from lupus patients also proliferated but secreted IL-10." (PMID 27487771, 2016). "Splenic B cells with a CD21+ CD23− MZ phenotype from lupus mice produce IL-10 in response to CpG stimulation." (PMID 27350539, 2016). "SLE patients present different cytokine response patterns to lupus-associated autoantigenic peptides compared to healthy donors, secreting significantly higher levels of IL-10." (PMID 27487771, 2016). "While IL-10 is generally considered an anti-inflammatory cytokine, serum levels are often raised in lupus patients where it can act as a potent B-cell growth factor, driving autoantibody production, class switching, and plasmablast differentiation." (PMID 27487771, 2016). "Although numerous miRNAs are found to be abnormally expressed in T cells, certain miRNA target lupus-related gene expression, including IL-10, IL-17, and DNMT1." (PMID 25988383, 2015). "Transfer of CD40-activated T2-MZP Bregs inhibited the development of lupus in recipient mice via the induction of IL-10-producing Tregs." (PMID 26071023, 2015). "On a more gene specific level, histone modification also regulates lupus-related cytokine secretion, such as enhanced H3 acetylation at the IL-17 locus and elevated IL-10 production by chromatin remodeling regulated by Stat3." (PMID 25988383, 2015). "Given that macrophages have been reported to be able to produce IL-10 in the lupus-prone MRL/lpr mouse we also assessed IL-10 production and Blimp1 expression in this compartment." (PMID 26544714, 2015). "MZ B cells from lupus-prone B6.TC mice produce more IL6 than WT mice whereas levels of MZ B cell-derived IL10 remain comparable." (PMID 26068236, 2015). "SCID mice injected with PBMCs from human lupus patients produced less IgG when treated with anti-IL-10 antibodies and similarly-treated mice showed less renal impairment after IL-10 blockade." (PMID 24945254, 2014). "The finding that IL-10 is present in higher concentrations in lupus patients than controls, and is elevated in SLE patients with active disease compared to inactive, further supports the notion that IL-10 contributes to lupus pathogenesis." (PMID 24945254, 2014). "To further understand if the IL-6 down-regulation in the presence of IL-10 is impaired in the B cells from lupus-prone TC mice, we measured the cytokine levels in the culture supernatants." (PMID 25093822, 2014). "One clinical trial of IL-10 blocking antibodies as a therapy for lupus has been reported that suggests there were benefits from this approach." (PMID 24945254, 2014). "Thereby, in mice with lupus-like autoimmune disease, splenic B cells with a CD1highCD23− marginal zone phenotype can produce IL-10 in response to CpG stimulation." (PMID 24478776, 2014). "The gene cluster that includes interleukin 10 (IL10), IL19, IL20 and IL24 is located on chromosome 1q31-32, a genomic region that is linked with susceptibility to systemic lupus erythematosus (SLE, OMIM 152700)." (PMID 24130510, 2013).
lupus (continued). "IL-10-deficiency also aggravates autoimmune pathology in a range of experimental models including rheumatoid arthritis (RA), experimental autoimmune neuritis, systemic lupus erythematosus (SLE), and experimental autoimmune encephalomyelitis (EAE)." (PMID 23755052, 2013). "Simvastatin was reported to decrease cytokine production, including IL-10, in a murine model of collagen-induced arthritis and in a murine lupus model, it decreased serum TNF-α and IFN-γ levels but increased transcription of IL-4 and IL-10." (PMID 24159421, 2013). "IL-10 has been reported to play immune-regulatory roles and its overexpression delays autoantibody production and clinical nephritis in lupus mice." (PMID 23935844, 2013). "Diminished disease severity resulted from the administration of IL-10 in the NZM2410 mouse model of lupus, and more severe disease occurred in MRL/lpr mice on the IL-10 KO background and in B10 cell-deficient NZB/W mice." (PMID 23638156, 2013). "Immunoregulatory cytokine interleukin-10 (IL-10) is elevated in sera from patients with systemic lupus erythematosus (SLE) correlating with disease activity." (PMID 24130510, 2013). "In summary, our results confirm that both Tfh cells and B10 cells are expanded in MRL/lpr mice and that Tfh cell-derived IL-21 is one of potent inducers for IL-10 production during the differentiation of B10 cells in a lupus animal model." (PMID 23638156, 2013). "Studies in lupus animal models and humans have shown that anti-IL-10 treatment can decrease disease activity in terms of clinical features and biologic markers." (PMID 23936042, 2013). "Administration of anti-IL-10 mAb to human patients with active lupus or NZB/W F1 mice led to the amelioration of disease activity." (PMID 22389703, 2012). "Lupus serum contains immune complexes and is able to induce the production of IL-6 and IL-10 from PBMCs." (PMID 23140401, 2012). "The results of this study demonstrated that artemisinin analogue SM934 had therapeutic effects on lupus-prone female NZB/W F1 mice by inhibiting the pathogenic helper T cell development and enhancing anti-inflammatory cytokine IL-10 production." (PMID 22389703, 2012). "By contrast, one study found poor IL10 induction and regulatory function in human lupus when focusing on the CD24highCD38high B cell pool." (PMID 23087687, 2012). "T2-MZP B cells also suppress other autoimmune diseases including antigen-induced arthritis (AIA) and lupus, and Schistosoma mansoni infection generates IL-10 producing T2-MZP B cells with regulatory function." (PMID 22969768, 2012). "In lupus, the levels of IL-10 found in the serum of affected patients correlate with the disease activity." (PMID 22321827, 2012). "Still another study, however, revealed comparable TLR9-induced secretion of IgM and IL-10 by PBMCs from lupus patients and healthy donors." (PMID 22952899, 2012). "The protective effect of IL-10 in mice appears to be mediated through T-cell regulation, as IL-10 overexpression in a mouse model for lupus resulted in reduced T-cell activation, while B-cell phenotypes remained unaffected." (PMID 23807906, 2012). "Continuous over-expression of low levels of IL-10 significantly delayed antinuclear auto-antibody production and decreased clinical nephritis in murine models of lupus." (PMID 27713252, 2010). "CD40L treatment of bone-marrow-derived DCs from lupus-prone B6.TC mice induced higher production of IL-6, IL-10, and TNF-α than in B6 mice." (PMID 18718031, 2008). "Furthermore, B cells from patients with systemic lupus erythematosus, despite impaired IL-10 production under conventional conditions, were efficiently differentiated into IL-10-producing B cells using this system." (PMID 42018652, 2026). "To characterize the mechanism by which gut microbiota could be regulating lupus manifestations, we then analyzed the frequency of IL-10-producing B cells." (PMID 40761803, 2025).
lupus (continued). "The reduced lupus inflammatory response was directly correlated with an increase of Parabacteroides distasonis, a reduction of intestinal permeability, and the induction of IL-10-producing B cells." (PMID 40761803, 2025). "Thus, our results illustrate a vital role of Hspa13 in promoting IL‐10 producing Bregs production and regulatory function, and partially elucidates the reason for the impaired regulatory function of the MZ B cells in lupus‐prone mice." (PMID 39737854, 2025). "Similarly, patients with systemic lupus erythematosus and rheumatoid arthritis, exhibited reduced counts of IL-10-producing B cells, which resulted in an inability to suppress the secretion of pro-inflammatory cytokine by T cells." (PMID 38728262, 2024). "However, recent studies have reported a relationship between miR-21, PDCD4, and IL-10 in patients with systemic lupus erythematosus." (PMID 39100039, 2024). "Interestingly, the concentration of IL-10 is often significantly increased in the aqueous humor of uveitic eyes, as well as in systemic lupus erythematosus patients." (PMID 39867889, 2024). "Thus, pseudotime trajectory analysis of IL-10+ B cells from lupus-prone mice revealed multiple pathways leading to the development of transcriptionally diverse Breg subsets present at different stages of disease progression." (PMID 38155972, 2023). "Overall, integrated clustering and separate cluster marker identification of pre-disease and active-disease IL-10+ B cells in similar biological states revealed key variations in analogous populations of regulatory B cells through disease progression in lupus-prone mice." (PMID 38155972, 2023). "This rise in salivary IgA1 concentrations must result from an overproduction of this antibody that could probably be related to the increments in systemic IL-10 levels as previously reported in lupus patients." (PMID 36911711, 2023). "Notably, this was in contrast to gene expression profiles of IL10-producing PB-PCs from lupus-prone mice, which were enriched for pro-inflammatory gene signatures and thus appeared more like IL10- cells from mice post-infection." (PMID 38155972, 2023). "To investigate the relationships among Breg subsets and to compare differences in populations identified at different stages of disease progression in lupus-prone mice, we carried out single-cell trajectory analysis to order IL-10+ B cells in pseudotime based on changes in gene expression." (PMID 38155972, 2023). "Furthermore, IL-10 treatment inhibited spontaneous systemic lupus erythematosus-induced kidney damage by inhibiting the Th1 response." (PMID 36142626, 2022). "IL-10 is a regulatory cytokine produced by B cells or certain CD+ 4 T cells and may have multiple roles in lupus, playing a major part in the stability of cellular and humoral immunity, with immunostimulatory and suppressive effects." (PMID 35359961, 2022). "In addition, we demonstrated that both RNASE2 and IL-10 in peripheral blood of lupus patients were mainly derived from monocytes." (PMID 35265065, 2022). "Furthermore, IL-10-producing putative regulatory B cells have also been reported to exert protective effects in lupus-prone mice." (PMID 36505422, 2022). "IL-10, TNF-α and IL-6 have been implicated in lupus pathogenesis." (PMID 36505418, 2022). "While TGF-β has been shown to drive the induction of CD103 expression in CD8+ iTreg, which in some circumstances has been shown to be a simultaneously cytotoxic and immunosuppressive T-cell subset, IL-10 has also demonstrated cytolytic characteristics during systemic lupus erythematosus (SLE)." (PMID 35493508, 2022). "It remains to be elucidated how RNASE2 regulates IL-10 production in lupus monocytes." (PMID 35265065, 2022). "Accordingly, B cell specific deletion of IL-10 in Lyn deficient mice, another lupus model, lead to increased disease severity, but did not alter plasma cell counts." (PMID 35979356, 2022).
lupus (continued). "This is an important finding considering celastrol can downregulate the signaling cascade of the SYK-MEK-ERK-NFkB, and the downregulation of IL-12 p40 (which correlates negatively with lupus SLE activity), which ultimately contributes to excessive IL-10 (positively correlated with lupus pathology)." (PMID 35431950, 2022). "The secretions of MSCs reduce serum IL-10 levels in lupus mice." (PMID 35908050, 2022). "Moreover, murine IL-10+ extrafollicular helper T cells were shown to provide B cell help and support the production of IgG antibodies in pristane-induced lupus and after immunization with the model antigen ovalbumin, in vivo." (PMID 35979356, 2022). "There have been numerous studies indicating that IL-10 may play multiple and opposing roles in murine lupus." (PMID 35979356, 2022). "While the hypothesis that LAP induces IL-10 to suppress lupus would predict that IL-10fl/fl LysM Cre+/– mice would have worse disease, in fact, we did not observe this for any parameter measured." (PMID 35192551, 2022). "Moreover, as our prior and current work do not show a role for myeloid and B cell–derived IL-10 in mediating lupus pathogenesis, by elimination, it is likely that T cell–derived IL-10 is the source of IL-10–regulating disease in MRL." (PMID 35192551, 2022). "Interestingly, the populations of MDSCs expressing immunoregulatory molecules including PD-L1, arginase-1, and IL-10 were significantly decreased in lupus patients." (PMID 33986739, 2021). "The prophylactic co-vaccination of IL-10 with D2 in pristane-induced lupus ameliorates the renal damage maybe by acting as prophylactic DNA tolerizing therapy." (PMID 34705865, 2021). "While continuous administration of α-IL-10 from 4 weeks of age onwards could delay autoantibody formation and lupus manifestation in NZB/W F1 animals, a deficiency of IL-10 in MRL-Faslpr mice induced lupus symptoms and autoantibodies." (PMID 33572870, 2021). "Interestingly, a similar correlation between IL-10 and Bregs was previously noted in systemic lupus erythematosus patients." (PMID 34573916, 2021). "Moreover, IL-10 overproduction in lupus induced lymphocyte apoptosis via the activation of Fas and caspase." (PMID 34960627, 2021). "The present study aimed to analyze the induction of antigen-specific tolerance after prophylactic immunization with a DNA vaccine encoding the epitopes: D183-119, D2, B ́/B, and B ́/BCOOH in co-vaccination with IFN-γ or IL-10 in a murine model of lupus induced by pristane." (PMID 34705865, 2021). "However, in vivo IL-10R blockade in mice with beginning lupus slightly accelerated disease progression, suggesting a rather protective role of IL-10 under these circumstances." (PMID 33572870, 2021). "Therefore, IL-10-producing Bregs are demonstrated to play protective roles during lupus progression." (PMID 34563233, 2021). "We further explored a possible connection between interleukin-27 (IL-27), STAT3 signaling and IL-10 expression in CD4 T cells of mice with manifest lupus and found that IL-27 transcripts were increased in the spleens of ill NZB/W F1 mice compared to healthy animals." (PMID 33572870, 2021). "Therefore, the aim of this study was to understand the regulation of IL-10 and IL-10R expression in the setting of lupus and their pro- versus anti-inflammatory effects on different target immune cells in this context." (PMID 33572870, 2021). "Interestingly, the mRNA levels of immunoregulatory molecules including PD-L1, arginase-1, and IL-10 were significantly decreased in lupus patients." (PMID 33986739, 2021). "Also, a study of the Sanroque mouse model of lupus displayed a similar phenotype with MDSCs inhibiting germinal center B cells, plasma cells and T follicular helper cells, while promoting IL-10-producing B cells." (PMID 32655565, 2020). "In addition, Th1 differentiation was suppressed by human B cells partially via IL-10 in systemic lupus erythematosus (SLE) patients." (PMID 33281813, 2020).
lupus (continued). "Whether activated Breg cells mitigated lupus in a IL-10 dependent manner, or through the production of other cytokines such as IL-35, will be investigated in the future." (PMID 33240280, 2020). "The severity of lupus in MRL mice were enhanced by the deletion of Il10 gene." (PMID 30816218, 2019). "The absence of CD137L causes an immune deviation toward Th17, fewer IL-10-producing CD11b+ cells and reduced serum IL-10 levels which potentially explain the more severe lupus in DKO mice while leading to reduced microglia activation, lesser cerebral damage and less severe neurological deficits." (PMID 31297111, 2019). "An analysis of anti-inflammatory cytokine IL-10 levels in the culture fluid of splenocytes derived from mice with lupus treated with TPC revealed increased IL-10 secretion by 12.5-fold compared to that from splenocytes originating from PBS-treated mice (P < 0.001)." (PMID 30801028, 2019). "Collectively, the absence of CD137L induces an immune deviation of CD4+ T cells by polarizing them towards the Th17 phenotype and reduces IL-10-producing CD11b+ cells and hence serum anti-inflammatory IL-10 levels, resulting in more severe lupus-related glomerulonephritis and dermatitis." (PMID 31500130, 2019). "The upregulated IFIT1 in lupus plays an important role in the production of cytokines IL-4 and IL-10, which may be related to the imbalance of Th1/Th2." (PMID 30836987, 2019). "TGF-β3 ameliorates IL-10-sufficient lupus-prone MRL/Faslpr/lpr (MRL/lpr) mice, but the requirement of both TGF-β3 and IL-10 in the regulation of other lupus models induced with a TLR7 agonist implies the importance of considering ICS when designing future therapeutic strategies." (PMID 30071700, 2018). "Other studies in IL-10 gene-deficient (IL-10−/−) MRL-Faslpr (MRL-Faslpr IL-10−/−) mice, however, suggest that IL-10 may play a suppressive role in lupus." (PMID 30257456, 2018). "However, the immunostimulatory effects of IL-10 on B cells and humoral immunity including lupus pathologies, and pleiotropic immunological roles of TGF-βs make application of these potent inhibitory cytokines elusive." (PMID 29963056, 2018). "However, in the patients with lupus, IL-10 levels were inversely correlated with depressive symptoms (p = 0.006, OR = 0.92), as has been seen for other diseases." (PMID 30148175, 2018). "FWGE has been reported to increase blastic transformation of peripheral blood T cells by concanavalin A, to reduce graft survival in a coisogenic skin transplantation model and to reduce production of IL-4 and IL-10 in a systemic lupus erythematosus model, supporting its immunomodulatory properties." (PMID 29304125, 2018). "The functional ex vivo assays showing increased frequencies of IL-10-producing B cells in Cd38−/− splenocytes than in WT upon stimulation with an agonist anti-CD40 mAb are in agreement with the in vivo experiments in the pristane-induced lupus model." (PMID 30257456, 2018). "IL-10 seems to act differently in lupus and rheumatoid arthritis, being disease suppressive in RA and disease promoting in lupus, which may help to explain the contrasting results observed in this study." (PMID 30148175, 2018). "In addition, disregulation of the IFN-alpha/pSTAT3/IL-10 axis in systemic lupus erythematosus patients has revealed that the levels of type 1 IFN produced by plasmacytoid dendritic cells dictate the formation of regulatory B cells in a STAT3-dependent manner." (PMID 27486189, 2016). "Finally, inhibition of select DLK1-Dio3 miRNA such as miR-154, miR-379 and miR-300 with specific antagomirs significantly reduced the production of lupus-relevant IFNγ, IL-1β, IL-6, and IL-10 in lipopolysaccharide (LPS) activated splenocytes from MRL-lpr mice." (PMID 27070142, 2016).